EPCAM (epithelial cell adhesion molecule)
Diseases named in the same sentence as EPCAM in open-access papers (continued):
Sharing a sentence is not in itself a finding about the gene and the disease.
tumor (continued). "However, in the HCT116 and SNU-5 models with high expression of EpCAM but low expression of CLDN3, the anti-tumor activity of BsADC 3 was close to EpCAM monovalent ADC, significantly lower than that of the EpCAM parental monoclonal ADC." (PMID 40057807, 2025). "To investigate TIC-derived GAS6 suppression of tumor immunity via AXL/MERTK on Reg-TAMs, we used Krt19-DreER Axin2-creER R26-Ai66 mice for AKT/YAP/SB hydrodynamic injection and sorted Reg-TAMs and epithelial cell adhesion molecule+/Tom+ (EpCAM+Tom+) TICs." (PMID 39774471, 2025). "To estimate the impact of mEp-NIR-PIT on non-cancer cells in TME, we first assessed EpCAM expression across various cell types in TUBO tumours." (PMID 40792441, 2025). "In tumour cells of epithelial origin, interactions between EGFR and EpCAM have been demonstrated." (PMID 39939830, 2025). "In xenograft tumor-bearing mice, M701 inhibited tumor growth but neither the anti-EpCAM antibody nor the anti-CD3 antibody performed such inhibition." (PMID 41275209, 2025). "We also observed EpCAM expression on patient-derived healthy endocervical cells, confirming that EpCAM is not tumor-specific." (PMID 41154384, 2025). "Circulating exosomes have higher levels of exosomal markers (CD63, CD81, and CD9), a few tumor antigens (carcinoembryonic antigen [CEA], CA125), and stemness markers (epithelial cell adhesion molecule [EpCAM], CD24), all of which may be useful for diagnosis." (PMID 40305328, 2025). "In conclusion, EpCAM represents an excellent target for NIR-PIT, as it is highly expressed in cancer cells while exhibiting minimal expression in essential immune cells within the tumour microenvironment." (PMID 40792441, 2025). "Improvements in enrichment technologies, marker selection for EpCAM-negative tumor cells, and analytical standardization will be essential prerequisites." (PMID 41514523, 2025). "On-target, off-tumor toxicities of ADCs can become dose-limiting in the clinic when choosing targets with low-to-moderate expression levels on normal tissues, such as TROP2, Epithelial cell adhesion molecule (EpCAM), and EPH receptor A2 (EphA2)." (PMID 40005994, 2025). "While CD44, E-cadherin, CD166 and EpCAM were expressed in the medial membranes of tumor cells, they were not expressed in the tumor buddings in a recent study." (PMID 40564019, 2025). "As previously demonstrated by our group, intracranial but not intravenous injection of EpCAM/GFPCAR T-cell results in sufficient tumor control." (PMID 39358663, 2024). "Epithelial cell adhesion molecule negative circulating tumor cells (EpCAM- CTCs) and EpCAM positive CTCs (EpCAM + CTCs) have different biological characteristics." (PMID 39280341, 2024). "Moreover, EpCAM+/ABCG2+ cells obtained from the BM tumor spheroids (Cisplatin ++ group), when injected to mice, showed induction of TSD phenotype similar to the parental EpCAM+/ABCG2+ cells." (PMID 39963656, 2024). "Of the top 20 differentially expressed proteins identified in tumour samples, four (MDH2, FASN, EPCAM, and HSD17B10) are targetable by FDA-approved drugs, whereas two (AMACR and GLYATL1) are potentially targetable and are of potential interest for future research." (PMID 38052461, 2024). "Most patients displayed a combination of EpCAMhigh, EpCAMlow, and EpCAM-negative tumor cells, while some individuals exhibited a complete absence of membrane EpCAM expression in all tumor cells, and others showed nearly total EpCAMhigh expression." (PMID 39456890, 2024). "However, as with CTCs, tumor cells were characterized by different combinations of the three CTC subsets, reflecting a marked interindividual heterogeneity of EpCAM expression on the membrane." (PMID 39456890, 2024). "EpCAM-negative CTCs and tumor cells, unlike EpCAMhigh CTCs, are also characterized by the presence of stemness features and a more frequent hybrid EMT phenotype, necessitating a closer study of their clinical significance." (PMID 39456890, 2024).
tumor (continued). "To identify hybrid cells in patient-matched tumor and peripheral blood, we applied a small panel of Ab-oligos against CD45, a pan-leukocyte marker, and an epithelial cocktail containing Ab-oligos to EpCAM, ECAD, and pan-Cytokeratin (panCK) to CRC and PDAC tumor tissue and matched isolated PBMCs." (PMID 38538742, 2024). "It has been reported that a smart conjugate composed of epithelial cell adhesion molecule (EpCAM) aptamer, dendrimer, polyethylene glycol (PEG), and celastrol specifically delivers celastrol into EpCAM-abundant tumor tissues to enhance the anticancer efficacy and reduce the toxicity." (PMID 38434700, 2024). "In tumour cells not expressing EpCAM other staining methods can be used such as Hoechst staining followed by nuclear morphological analysis." (PMID 39376603, 2024). "Anti-EpCAM CAR-T cells targeting epithelial cell adhesion molecule (EpCAM) inhibited the progression of CRC in tumor-bearing mice without inducing obvious toxic side effects." (PMID 38254219, 2024). "SNAI1, CDH1, and FN1 gene expression was detected more frequently in EPCAMlow than in EPCAM-negative primary tumor spots." (PMID 39456890, 2024). "We also found a negative correlation among EpCAM-negative CTCs when considering the EMT features of tumor cells between CK7/8−E-cadherin−panCK+N-cadherin− and CK7/8−E-cadherin+panCK+N-cadherin− (r = −0.64, p = 0.036)." (PMID 39456890, 2024). "A novel human IgG1 anti-EpCAM antibody, adecatumumab (MT201), exhibited dose-dependent anti-tumor activities and hightolerance for metastatic breast cancer (MBC), primarily through effector functions such as antibody-dependent cellular cytotoxicity (ADCC) and complement-dependent cytotoxicity (CDC)." (PMID 39595576, 2024). "Moreover, the tumor organoids expressed specific markers for hepatocytes (AFP/hepatocyte nuclear factor 4α) and cholangiocytes (epithelial cell adhesion molecule [EpCAM]/cytokeratin 19)." (PMID 39192365, 2024). "Although more than 1000 studies have investigated EpCAM immunostaining at least in common tumor types (PubMed, 12 September 2023), EpCAM has not or has only rarely been investigated in many other tumor entities." (PMID 38786342, 2024). "We also performed a correlation analysis between the proportion of EpCAMhigh, EpCAMlow, and EpCAM-negative cells in the primary tumor and CTCs." (PMID 39456890, 2024). "In some cases, all circulating tumor cells (CTCs) were represented by only one subpopulation, either EpCAMhigh or EpCAM-negative cells." (PMID 39456890, 2024). "Interestingly, the cisplatin++ group mirrored the cisplatin+ group by exhibiting an increase in EpCAM+/ABCG2+/pimonidazole+ CTCs between the 2nd and 8th week of tumor growth." (PMID 39963656, 2024). "This combination reduces off‐target toxicity toward nonmalignant cells with normal EpCAM expression levels, to direct reactivity toward tumor cells with high expression." (PMID 39618102, 2024). "For this purpose, more than 14,000 tissue samples from 120 different tumor types and subtypes and 76 non-neoplastic tissues were evaluated for EpCAM protein expression by IHC in a tissue microarray (TMA) format." (PMID 38786342, 2024). "Notably, its simultaneous targeting of both EpCAM and CD133 epitopes provides a dually specific attack on tumour cells and the pivotal CSCs." (PMID 39472273, 2024). "Here, we evaluated the expression of PD-L1, EGFR, rVAR2, and EpCAM on different NSCLC cell lines and concluded that the combined use of rVAR2 and EpCAM enhances the efficiency of immunomagnetic enrichment for tumor cells with varying levels of target expression." (PMID 39337304, 2024). "G9a, for instance, promotes tumor cell growth and invasion in NSCLC by silencing cysteine aspartic acid specific protease (CASP1) and the cell adhesion molecule epithelial cell adhesion molecule (EpCAM) through increased H3K9me2 around promoters." (PMID 38525426, 2024).
tumor (continued). "First, we collected cancer cells (CD45-EpCAM+) and immune cells (CD45+EpCAM-) via FACS from the tumor mass of 4T1 tumor-bearing mice either with or without clodronate treatment." (PMID 38169569, 2024). "Consistent with previous reports, MMP14 and OPN expression was also detected on tumor macrophages and EpCAM+ tumor cells, however, at 2- to 3-fold lower levels compared with TANs, indicating TANs as a major source of MMP14 and OPN in the CRC tumor niche." (PMID 38329810, 2024). "Tumour sections showed no significant lymphocyte infiltration in each group, which indicated better targeting of EpCAM-CAR-T cells." (PMID 39107717, 2024). "Importantly, EpCAM and CD45 stainings of consecutive tumor sections verified a much higher immune cell infiltration in TN tumors than ER+ tumors." (PMID 39246414, 2024). "EpCAM driven classification managed to reach 91% AUC with 89% balanced accuracy on the CTC test set and only 53.7% AUC on primary tumor set, as opposed to 95% balanced accuracy on the CTC test set and 99% on the primary tumor set." (PMID 38744942, 2024). "CTCs are tumour cells shed from the original tumour and are identified via the presence of specific proteins (e.g., the presence of EpCAM and CK8/18/19 or the absence of CD45)." (PMID 38254750, 2024). "The results similarly revealed significant positive correlations between the expression levels of EpCAM (r = 0.78, p = 0.022), CD51 (r = 0.82, p = 0.014), and CD49b (r = 0.85, p = 0.007) in tumor tissues and those observed in paired EVs isolated from plasma samples." (PMID 39479442, 2024). "Taken together, tumor NOS2 and COX2 expression collaborates during the metastatic process, which may involve at least in part the upregulation of EpCAM expression." (PMID 39356141, 2024). "Assessment of epithelial marker genes showed similar expression scores across fresh and FFPE tissue samples, as EPCAM, KRT5, SCGB3A2, FOXJ1, AGER and SFTPC marked tumor epithelial, Basal, Transitional, Ciliated, AT1, and AT2 cells, respectively, across the datasets." (PMID 38300468, 2024). "Comparison of the three groups of patients—divided by the proportion of EpCAMhigh, EpCAMlow, and EpCAM-negative CTCs—by molecular subtype, tumor size, grade, and lymphogenous metastasis did not reveal any differences." (PMID 39456890, 2024). "In the EpCAM/OVCAR-5 model, FLRT3 expression on tumors significantly reduced T cell–mediated antitumor immunity, inhibited T cell TME recruitment/infiltration, and reduced T cell engagement (close interaction) with tumor cells." (PMID 38427724, 2024). "In addition to an enrichment in stem pathways, EpCAM+Sca-1+CD133+ cells also displayed a gene expression profile enriched in innate immunity and tumour immune evasion signatures." (PMID 38754953, 2024). "Moreover, the MFI values of the epithelial surface markers EpCAM and TROP2 were also very low in NT samples when compared to tumor samples (BCa)." (PMID 39084491, 2024). "This study also explored the cytotoxic impact of anti-EpCAM-CAR-T on tumour cells exhibiting both positive and negative EpCAM antigen expression, both in vitro and in vivo." (PMID 39107717, 2024). "The staining was confined to larger, EpCAM positive, epithelial tumor cells, and was negative in non-tumor cells (such as CD3 T cells, for example)." (PMID 39086481, 2024). "This indicates that, at least for the listed manifestations of tumor disease, EpCAM-negative CTCs are not less pronounced than cases with a predominance of EpCAMhigh CTCs." (PMID 39456890, 2024). "Similar to what we found in vivo, EMT tumour cells were profoundly resistant to chemotherapy in vitro in the absence of the tumour microenvironment, whereas EPCAM+ epithelial tumour cells were even more sensitive." (PMID 36949199, 2023). "EphA2-TEA-OVV, which expresses a bispecific T cell engager targeting CD3, EphA2, or EpCAM, exhibits notable anti-tumor activity and bystander killing of non-infected tumor cells." (PMID 37615308, 2023).
tumor (continued). "The most commonly used techniques to detect CTCs from the peripheral blood are the CellSearch system (the gold standard), the CTC chips, and the Isolation by Size of Epithelial Tumour Cells (ISET) filter device, with the first two employing EpCAM for CTC identification." (PMID 36675033, 2023). "In contrast to EpCAM, pan-keratin staining did not identify cells in the stroma surrounding metastatic tumours." (PMID 37975646, 2023). "In urothelial cancer, EpCAM and its fragments should not be regarded as tumor-specific without prior patient-specific predictive testing." (PMID 37154925, 2023). "Additionally, the EpCAM-CLDN-7 complex strongly promotes tumorigenicity, accelerates tumor growth, and promotes ascites production and thymic metastasis formation." (PMID 36959784, 2023). "The proportion of cells with nuclear actin fibres was increased in EPCAM− tumour cells compared with in EPCAM+ and Rhoj-KO tumour cells in the presence or absence of cisplatin/5FU, showing that RHOJ controls nuclear actin polymerization." (PMID 36949199, 2023). "While the algorithm identified the fibroblasts according to the expression of EpCAM in all datasets, further clustering was performed based on the estimated expression of FOLR1 and aSMA in the pan-tumor and merged datasets and CD73 expression in the merged dataset." (PMID 37894472, 2023). "After excluding potential low‐quality cells and removing a cluster with high expression of epithelial markers (such as EPCAM, KRT8, KRT19) to distinguish fibroblasts from tumour cells undergoing epithelial‐mesenchymal transition (EMT), 13 subclusters of fibroblasts were retained." (PMID 38115703, 2023). "EpCAM was not tumor-specific, neither across tumor stages, nor in a pooled comparison or by individualized expression profiles." (PMID 37154925, 2023). "Isolation of CD56+ CTC using an immunofluorescence-based EpCAM-independent method at diagnosis is feasible in SCLC and might capture more efficiently tumor genomic heterogeneity." (PMID 36869231, 2023). "Softening EpCAM− cells (non-CSCs) increased the EpCAM+ fraction (CSCs) by 40 to 84% and the formation and growth of tumor spheroids by 150 to 250% and 230 to 300%, respectively." (PMID 37746658, 2023). "The expression of these commonly used tumor-specific antigens, such as EpCAM, is not stable on the CTC surface." (PMID 38001632, 2023). "In this study, we sought to combine three tumor markers, CK20, EpCAM, and Pan-CK, through triple-parameter FCM (tFCM), with the aim of evaluating whether tFCM could enhance the precision and efficiency of LN metastasis detection in CRC patients." (PMID 38152574, 2023). "We first assessed EpCAM epithelial marker expression in control versus NP137-treated tumours, and observed a statistically significant increase of this epithelial marker in NP137-treated tumours." (PMID 37532934, 2023). "Another study showed that EpCAM-CAR T cells had potential even for stage IV disease, where intratumoral (IT) injection of these cells into intracerebral lung carcinoma tumors reduced tumor growth and increased murine survival." (PMID 38067366, 2023). "Imaging the tumour body and adjacent stroma in sections of human OSCC specimens, we detected single cells co-expressing EpCAM, Vimentin and CD24 in the stromal region surrounding the tumour, confirming that these cells can be detected in human tumour specimens." (PMID 37975646, 2023). "A phase I clinical trial indicated that VB4-845 successful blocks tumor growth in patients with high EpCAM expressing non-muscle-invasive bladder cancer." (PMID 37853413, 2023). "Further evidence for a tumor-promoting role of BAMBI came from the high expression of BAMBI in tumors with overexpression of the hepatic stem cell marker, epithelial cell adhesion molecule (EpCAM)." (PMID 36834884, 2023).
tumor (continued). "A decrease in tumor sphere formation and CaP progression was observed in CaP cells when EpCAM was targeted, with a significant decrease in PI3K/AKT/mTOR expression, suggesting that EpCAM can be the therapeutic target to inhibit CaP progression." (PMID 37895357, 2023). "In addition, this sensing platform can determine four different tumor cell types (4T1, Hela, HepG2, and A549) using surface proteins corresponding to aptamers 1 and 2 (CD63 and EpCAM) and showcases good specificity in serum samples." (PMID 37050576, 2023). "Higher expressions of EPCAM, β-catenin, β-catenin (in the nucleus), c-Myc, and SOX2 were observed in the EPCAMhigh cells derived xenografted tumor tissues than in the EPCAMlow cell-derived xenografted tumor tissues (p < 0.05)." (PMID 36674577, 2023). "Additionally, RT‐qPCR analysis of RNA extracted from the EPCAM+ cell subpopulation, comprising mainly the cancer cells, revealed higher levels of IL23 and SERPINE1 mRNA in the WT tumours as compared to the TAZ‐KO tumours." (PMID 37716913, 2023). "EpCAM single, Bi-dual, and Tan-dual CAR T cells produced significant tumor responses against subcutaneous MKN-45, ranging from partial to complete with some animals displaying fluctuations in the tumor burden." (PMID 38067255, 2023). "CD44+EpCAM (high) cells sorted from AGS cells subjected to gain-of-function experiments, followed by evaluation of their capacity of colony formation, generation of tumorosphere, cell migration and viability in vitro and xenograft tumor formation in vivo." (PMID 36765401, 2023). "Third-generation EpCAM-CAR-T cells were cytotoxic to target cells and induced lysis in them in an EPCAM-dependent manner leading to notable regression of tumor growth and secretion of cytotoxic interferon gamma (IFN-γ) and tumor necrosis factor alpha (TNF-α) in the MDA-MB-231 model." (PMID 37457288, 2023). "Additionally, the protein levels of SNAI2, EPCAM, β-catenin, c-Myc, and SOX2 were detected in xenografted tumor samples formed by SiHa-Vec and SiHa-SNAI2 cells." (PMID 36674577, 2023). "SELEX has tested a number of aptamers targeting tumor cells, for example, A10 aptamer (against prostate-specific membrane antigen; PSMA), AS1411 aptamer (against nucleolin), EpCAM aptamer (against epithelial cell adhesion molecule), and Sgc8 aptamer (against protein tyrosine kinase 7; PTK7)." (PMID 37149607, 2023). "Therapeutic activities have been confirmed in the clinical use of anti-EpCAM mAbs without concern for pancreatic toxicity; however, no objective tumor regression was observed." (PMID 36918661, 2023). "Moreover, the protein levels of SNAI2, EPCAM, β-catenin, c-Myc, and SOX2 were also detected in EPCAMhigh-and EPCAMlow-cell-derived xenografted tumor tissues." (PMID 36674577, 2023). "Additionally, the proportion of CD24, EpCAM, CD13, or CD133 positive cells were reduced in SCARB2 knockout tumor organoids." (PMID 37739936, 2023). "The spheroid population was composed almost exclusively of EpCAM+ and CD24+ tumor cells." (PMID 38248751, 2023). "The difference in staining between tumour and non-tumour margin tissues with EpCAM was significant (p < 0.001)." (PMID 37533952, 2023). "In addition, IHC staining was performed, which showed efficient tumor cell lysis and reduced numbers of tumor cells in MeV-DsRed-infected compared to MOCK-treated co-cultures, as indicated by staining with H&E and EpCAM antibody." (PMID 36851574, 2023). "For non-immune cell populations, we identified tumor cells (EPCAM and CLDN4), fibroblasts (COL3A1 and NNMT), and mesothelial cells (LRRN4 and WT1)." (PMID 36788228, 2023). "Subsequent plots of responders in terms of tumor area reduction and tumor death increase revealed a correlation between responder status and EpCAM expression; however, this was not statistically significant." (PMID 37190054, 2023).